STAT1 (signal transducer and activator of transcription 1)
Diseases named in the same sentence as STAT1 in open-access papers (continued):
Sharing a sentence is not in itself a finding about the gene and the disease.
tumor (continued). "Some spontaneous human tumors have been reported to be selectively unresponsive to IFN-γ due to impaired STAT1 activation and this suggests that as in mouse models, the IFN-STAT1 dependent tumor surveillance mechanism also engages in humans." (PMID 26351076, 2015). "STAT factors can either inhibit (mostly STAT1) or support (mostly STAT3 and STAT5) tumour cell proliferation." (PMID 25880691, 2015). "The balance between STAT1 and STAT3 activation within a tumour is paramount for the resulting effects on the tumour cell itself and the microenviroment." (PMID 25880691, 2015). "We assessed USP18 mRNA and protein levels in B16 tumor cells after IFN-α or IFN-γ stimulation and found that IFN-γ was a more potent inducer than IFN-α for USP18 expression, as well as Stat1 phosphorylation, which is IFN-γ signaling downstream gene." (PMID 24884733, 2014). "These two TFs are directly involved in pancreatic tumorigenesis and proliferation, and are thought to play opposite roles - while STAT1 promotes apoptosis, STAT3 is essential for the proliferation and survival of tumour cells." (PMID 25521701, 2014). "If the STAT1-dependent expression of MHC proteins is enhanced, tumor proliferation and survival are inhibited by the activation of IFN-γ." (PMID 24497942, 2014). "Among the STAT1 targets investigated in our study, MX1 and CXCL10 can be considered as genes influencing tumor progression, since their expression was significantly associated with bad patient‘s prognosis." (PMID 24725474, 2014). "We analyzed the concentration of CXCL10 in preoperative sera and tumor samples of 10 patients and compared these values with the expression levels of CXCL10 and STAT1 mRNA in the tumor." (PMID 24725474, 2014). "In particular, IFN-γ acts directly on tumor cells in mice to up-regulate MHC class I, whose higher expression is correlated with greater STAT1 activation, leading to a tumor microenvironment conducive for T cell infiltration and tumor cell target recognition." (PMID 24434638, 2014). "STAT1, another member of the STAT family, is activated by IFN-γ and has multiple tumor suppressor functions such as enhancement of immune surveillance and promotion of apoptosis." (PMID 24743777, 2014). "Interleukin-27 signaling is mediated by the JAK-STAT pathway via activation of STAT1 and STAT3, which have tumor suppressive and oncogenic activities, respectively." (PMID 24274066, 2013). "IFN-у/STAT1 signaling can have tumor suppressor function and IFN-у treatment is recommended and tested in tumor therapy." (PMID 24058673, 2013). "Because tumor cells commonly overexpress STAT1 and ZOL reportedly radiosensitizes various types of tumor cells, ZOL warrants further clinical and translational studies as a potent radiosensitizer against RT-resistant tumors overexpressing STAT1." (PMID 23741352, 2013). "Although the anti-tumor properties of IL-27 have been described previously, our study describes a new mechanism by which IL-27 inhibits EMT and angiogenesis through a STAT1 dominant pathway." (PMID 24274066, 2013). "Priming of tumor cells with suboptimal concentration for short duration can significantly enhance anti-tumor activity of EGFRBi armed ATC through the inhibition of Stat3 and activation of Stat1." (PMID 23185240, 2012). "The expressions of several drug-resistant genes including MDR1, GAGE, STAT1, and MAP7 were found to be overexpressed in three Pyk2 overexpressing HCC cell lines and in tumor liver tissues of HCC patients." (PMID 22096562, 2011). "STAT1, a transcription factor upstream of IRF1 and mediator of IFN signaling, is also considered a tumor suppressor gene." (PMID 22295238, 2011). "STAT1 is believed to have an essential role in CTL- and NK-cell cytotoxicity; both lymphoid lineages are important mediators of tumor surveillance." (PMID 22185785, 2011).
tumor (continued). "Activated STAT1, STAT3 and STAT5 are often observed in solid and liquid tumors, and are required for tumor transformation and progression which involves a set of oncogenes such as EGFR, Ras, Src, and FAK." (PMID 20576130, 2010). "We previously demonstrated that stable KD of STAT1 in nu61, a radioresistant derivative of the SCC61 tumour cell line, led to decreased tumour growth and sensitization to IR." (PMID 19891767, 2009). "The Signal Transducer and Activator of Transcription 1 (STAT1) has traditionally been regarded as a transmitter of interferon signaling and a pro-apoptotic tumour suppressor." (PMID 19891767, 2009). "Thus, changes in energy-related metabolic pathways may provide growth advantages to tumour cells and support aggressive tumour phenotypes, and STAT1 may be a valuable target for antitumour therapy directed towards energy depletion of proliferating tumour cells." (PMID 19891767, 2009). "Previously, we demonstrated that a radioresistant tumor (Nu61), selected against fractionated ionizing radiation (IR) from a radiosensitive parental tumor SCC61, constitutively overexpresses the IFN/STAT1 pathway." (PMID 19503789, 2009). "The individual lung colonies, which are believed to be the progeny of a single lung colonizing tumor cell, were used to establish cell lines in which we examined levels of expression of the IFN/STAT1 pathway." (PMID 19503789, 2009). "Constitutively activated signal transducers and activators of transcription (STAT) factors, in particular STAT1, STAT3 and STAT5, have been demonstrated in a variety of human tumours and cancer cell lines." (PMID 12865928, 2003). "This review synthesizes mechanistic evidence showing how JAK/STAT signaling, predominantly through STAT1 and STAT3, integrates inflammatory cues, oncogenic stress, and microenvironmental signals to regulate PD-L1 expression across tumor cells and immune compartments." (PMID 41858895, 2026). "Moreover, transcriptomic and Q-PCR analyses showed increased expression of Stat1, Zbp1, Parp14, Irf1, and Tifa along with decreased Eif4e2 in the SOR treatment group compared to the tumor control group." (PMID 42194025, 2026). "The IFNγ pathways shared the downstream IRF1 and STAT1 molecules that bound with the promoters of PD-L1 and CXCL10, enhancing the efficacy of anti-PD1/PD-L1 inhibitors and boosting T-cell infiltration in the tumor microenvironment." (PMID 40149259, 2025). "During anti-PD-1 therapy, treatment of Flu in B16-F10 bearing mice did not alter the proportion of CD11b+Ly-6G+ neutrophils, indicating that STAT1 inhibition did not affect neutrophils infiltration into tumor tissue." (PMID 40226609, 2025). "Additionally, HKDC1 facilitates tumor immune escape by recruiting cytoplasmic STAT1 to IFNGR1, thereby revealing its critical role in the tumor immune microenvironment and providing theoretical support for combined immunotherapy." (PMID 40692442, 2025). "Furthermore, the effects of aspirin on IFN-α–induced activation of STAT1 and induction of COX2 were evaluated in tumor tissues using Western blot assays." (PMID 39826687, 2025). "We analyzed the role of ICDRs in tumor immune microenvironment by using the previous data of single cell transcriptome, and we analyzed the distribution of several key genes (PSME2, TYMP, KLHDC7B, GBP5, EPSTI1, STAT1 and OAS2) in different cell types." (PMID 40259929, 2025). "The analysis of various tumor cell lines revealed that vitcylation is a widely used mechanism of phosphorylation (and therefore activation) of STAT1 but not STAT2 nor STAT3." (PMID 40583064, 2025). "We next checked the activating phosphorylation sites of STAT1 and observed an increase in signal when MK-2206 was additionally applied to tumor organoids with and without macrophages." (PMID 41429766, 2025).
tumor (continued). "MHC I expression on tumor cells is highly variable and can be influenced by several factors, such as Th1-secreted (T helper cells) cytokines and TKIs which have been shown to enhance MHC I expression by activating the IFN-γ/STAT1 signaling pathway." (PMID 41019037, 2025). "HNSCC: Patients who received Met before surgery had enhanced tumor infiltration of NK cells, which inhibited the CXCL1 pathway, while stimulating the STAT1 pathway within HNSCC NK cells, which enhanced NK cytotoxicity and prolonged overall survival when combined with chemoradiotherapy." (PMID 40161377, 2025). "In contrast, STAT1 and STAT2 often play tumor-suppressive and immunoprotective roles." (PMID 41438753, 2025). "Hsa-miR-138-5p was enriched in immune signaling, Hippo, and apoptosis pathways, suggesting it may act as a tumor suppressor by targeting genes such as MYD88 and STAT1." (PMID 40869426, 2025). "However, evidence suggests that STAT1 also emphasizes tumor-promoting functions, while STAT3 also acts as a tumor suppressor protein targeting genes involved in apoptosis and growth arrest." (PMID 39942749, 2025). "Taken together, all these data might hint on the possible inhibitory role of FAM210B on tumor angiogenesis and metastasis in LUAD through IFN-α/β/ STAT1 signal axis." (PMID 39900908, 2025). "Consequently, tumor-derived lactate orchestrates and sustains malignant progression in PTC through this “H3K18la-STAT1-LDHA” regulatory axis." (PMID 41208879, 2025). "Specifically, IL-11 activates STAT3 phosphorylation, which inhibits IFNγ-induced STAT1 phosphorylation, thereby downregulating MHC-I and CXCL9 expression in tumor cells and impairing CD8+ T cell infiltration—promoting immune evasion and tumor growth in CRC." (PMID 41359051, 2025). "In this study, we found that p-STAT1 and p-STAT2, the key transducers of IFN-I signaling, can also be transferred from tumor cells to macrophages via secretory autophagy, thereby realizing the transmission and spread of IFN-I signaling between tumor cells and macrophages." (PMID 41321309, 2025). "This elevated level of tyrosine-phosphorylated STAT1-ΔN did not further increase upon stimulation of isolated tumor cells with either interferon-γ (IFNγ), lipopolysaccharide (LPS), or the combination of both." (PMID 40287766, 2025). "Therefore, the combination therapy with TTFields and anti-PD-1 activates STAT1 and IRF1 through ICD in tumor tissue, enhancing the CCL2/8-CCR2 axis and CXCL9/10-CXCR3 axis, which recruits CD8+ T and CD4+ T cells to infiltrate and kill tumor cells." (PMID 40098106, 2025). "This suppression of STAT1- and STAT3-target genes suggests that chalcone-9 may disrupt tumor cell functions related to those genes." (PMID 40199813, 2025). "Besides, the results of tumor microenvironment analysis suggested that ANXA5, STAT1, CD44, CAV1, and ANXA2 expression was positively correlated with the infiltration of B cell, CD8+ T cell, CD4+ T cell, macrophages, neutrophils, and dendritic cells." (PMID 40607003, 2025). "Emerging evidence suggests that modulation of the immune response through inhibition of these kinases, particularly via the cGAS-STING pathway and STAT1/STAT3 transcription factors, which activate a type I interferon response and upregulate PD-L1, contributes to anti-tumor immunity." (PMID 40977887, 2025). "Recent findings have elucidated that in gastric glandular cancer, regulated by IFN-γ/STAT1 signaling, the upregulation of CXCL10 correlates strongly with the degree of CD8+ T cell infiltration in the tumor microenvironment, thereby bolstering antitumor immunity." (PMID 40909948, 2025). "Mice lacking the IFN-γ receptor and STAT1 have a significant increase in chemical tumor growth after exposure to chemical carcinogens, demonstrating IFN-γ's anti-cancer ability." (PMID 40259042, 2025).
tumor (continued). "Notably, mutations in the IFN γ receptor (IFNGR1 and IFNGR2) and downstream signaling molecules, such as STAT1, have been identified as key factors in resistance, as they impair the signaling cascade necessary for IFN-γ-mediated tumor cell death." (PMID 40805243, 2025). "BIN-1, previously characterized as a tumor-suppressor gene, has been shown to act as a transcriptional repressor of the IDO-1 gene through pathways involving signal transducers as well as activator of transcription 1 (STAT1) and NF-κB." (PMID 39859561, 2025). "Thus, the activation of the IFN-γ/JAK/STAT1/IDO1 pathway contributes to immune escape in gastrointestinal tumors via its effects on various cell types, including T cells and tumor cells." (PMID 40909948, 2025). "The mechanism behind this remains unknown, but tumor cells may accumulate DNA fragments in the cytoplasm, activating the cGAS/STING pathway and subsequently STAT1." (PMID 41367865, 2025). "The IFN-γ/STAT1 pathway upregulates the expression of IFIT2, leading to the initiation of apoptosis by modulating the balance between anti- and pro-apoptotic factors, thereby regulating mitochondrial permeability and inducing the death of tumor cells." (PMID 40909948, 2025). "The released IL-10 activated the STAT1/STAT3 signaling pathway to alleviate CAP-induced endoplasmic reticulum stress in tumor cells, finally resulting in attenuation of programmed death of tumor cells after CAP exposure." (PMID 41145470, 2025). "Consequently, inhibiting STAT1/3 or NF-κB using the STAT inhibitor Stattic or the IKK inhibitor IMD-0534, also suppressed IκBζ-dependent, self-sustained tumor cell proliferation in MV3 cells." (PMID 40562773, 2025). "Chitosan-based systems demonstrate tumor-suppressive potential by inhibiting Programmed Death-Ligand 1 (PD-L1) upregulation via AMP-activated protein kinase (AMPK) activation and Signal Transducer and Activator of Transcription 1 (STAT1) suppression." (PMID 41149588, 2025). "Challenged with chemical carcinogens, mice lacking STAT1 showed more rapid and frequent tumor development." (PMID 40241721, 2025). "Moreover, increased IFNGR expression by nPD-L1 was also observed, and subsequently, nPD-L1 dramatically increased the expression of p-STAT1 in Hep3B cells compared with vector in response to IFN-γ, indicating the enhanced IFN-γ response of tumor cells." (PMID 39545415, 2024). "Besides, retinoic acid-inducible gene I (RIG-I) is a multifunctional protein that can interact with signal transducer and activator of transcription 1 (STAT1), which acts as a switch in anti-tumor activity." (PMID 39055888, 2024). "Instead of employing a strategy to restore STAT1 expression to enhance sensitivity to treatment interventions, we found that direct administration of our candidate DNA vaccine CRT/E7 alone was sufficient to control tumor growth in STAT1−/− mice." (PMID 38675812, 2024). "Nevertheless, the implication of STAT1/RIG-I axis in EMT and tumor growth in MM is still unclear." (PMID 39055888, 2024). "It was found to facilitate tumor cell apoptosis and may be a tumor suppressor gene through involving the JAK/STAT1 pathway." (PMID 39737399, 2024). "Previous studies reported that the inflammatory factor of IFN‐γ could drive PD‐L1 upregulation in tumor cells through the Janus kinase (JAK)/signal transducer and activator of the transcription‐1 (STAT‐1) signaling pathway." (PMID 38460167, 2024). "Gene expression mRNA level analysis exhibited significant upregulation of mRNA levels in tumor tissue: IFNAR1 (3.4-fold increase, p < 0.0001), IRF9 (4.2-fold increase, p < 0.0001), STAT1 (7.1-fold increase, p < 0.0001), and IFI27 (66.3-fold increase, p < 0.0001)." (PMID 39457004, 2024). "IFNγ could induce the expression of IFITM3 and STAT1, and the IFITM3 cKO mice showed higher IFNγ expression in the tumor environment to mediate a more robust anti-tumor response." (PMID 38167862, 2024).
tumor (continued). "STAT1 is a crucial mediator of IFN signaling and is considered a tumor suppressor." (PMID 38893499, 2024). "Our study strictly focuses on the effect of STAT1 expression on the host immune system, and not on the tumor microenvironment." (PMID 38675812, 2024). "NKILA is induced in activated T cells by STAT1 (signal transducer and activator of transcription 1) in a calcium/calmodulin-dependent fashion and promotes AICD in tumor-specific cytotoxic T lymphocytes and T helper cells type 1 (TH1) via the inhibition of the NF-κB pathway." (PMID 37782337, 2024). "Conversely, many genes have broad, often bi-/multimodal distribution (for example CD44, CCND1 and CD74 in tumour and STAT1 in both compartments for all p16/HPV subgroups), potentially reflecting spatial context – tumour core versus tumour periphery or tumour-adjacent versus more distant stroma." (PMID 39328208, 2024). "For IFNGR2, STAT1 and MYC, both sgRNA pools significantly increased the number of eGFP positive 2D3TCR/dCas9 cells (right), in line with their role as positive regulators of PD-L1 expression in tumor cells." (PMID 39497819, 2024). "Additionally, OASL regulates immune checkpoint ligand such as programmed death ligand 1 (PD-L1), through IFN-γ/STAT1 and IL-6/JAK/STAT3 pathways in tumor cells." (PMID 39286258, 2024). "It is hypothesized that IL-10 could phosphorylate and activate STAT1, STAT3, STAT5, and PI3K pathways, exerting apoptosis regulation and tumor progression functions on immune cells." (PMID 38279997, 2024). "STAT1/ STAT2 has a large number of target genes, including NO, BCL-2, p21, and CCND1, which all participate in pro-apoptotic and cell-cycle regulation, and act as tumor suppressors in various cancers." (PMID 38191598, 2024). "Furthermore, when STAT1 (a key component in the IFN-γ pathway) was knocked down in squamous cell carcinoma cells, tumor cell invasion was suppressed in a subcutaneous tumor transplantation model." (PMID 40741180, 2024). "Finally, we experimentally verified the differential expression of LAMP3 in UCEC and normal tissues, its effect on tumor cell invasion and migration ability, and its effect on the expression of the MX2 and STAT1." (PMID 38217544, 2024). "Since the STAT1-IFITM3 feedback loop depends on IFNγ, our research also provides innovative sights of targeting Treg perturbation to regulate anti-tumor immunity in the IFNγ-enriched tumor microenvironment." (PMID 38167862, 2024). "The heterodimeric IFNGR1/IFNGR2 receptor complex on tumor cells binds to IFN-γ released by tumor-specific T lymphocytes, activating JAK1 and JAK2, which subsequently phosphorylate a transcription factor known as STAT1." (PMID 38785789, 2024). "We found that STK24 deficiency in tumor cells significantly impaired the phosphorylation of AKT, but not STAT1 and STAT3 when cells were exposed to IFN‐γ." (PMID 38229183, 2024). "The deletion of PTPN2 in T cells not only promoted the activation and cytotoxic potential of tumor-infiltrating/resident T cells (as reflected by IFNγ, TNF and GZMB levels), but also enhanced STAT-1 signaling in AT3-OVA tumor cells, the expression of Cxcl9 and the recruitment of T cells." (PMID 37500611, 2023). "Most significantly, in vivo experiments showed that the administration of butyrate led to the suppression of STAT1 signaling, down-regulation of PD-L1, and a decrease in infiltration of CD8+ T-cells that resulted in facilitating immune clearance and tumor growth suppression." (PMID 37931529, 2023). "NF-κB and signal transducers and activators of transcription 1 (STAT1) can also induce pyroptosis by regulating Caspase-1 or GSDMD protein expression, accompanied by a large release of inflammatory factors, which acts as a tumor growth suppressor." (PMID 36744134, 2023). "Using a high throughput screen of compounds that could enhance STAT1-dependent gene expression, a compound called 2-NP was identified as an enhancer of the inhibitory effect of IFN-γ on proliferation of tumor cells." (PMID 38022653, 2023).